KSR1 (kinase suppressor of ras 1)
Diseases named in the same sentence as KSR1 in open-access papers (continued):
Sharing a sentence is not in itself a finding about the gene and the disease.
meningioma (2 papers, 2020 to 2024). A generally slow growing tumor attached to the dura mater. "We show that KSR1 is also increased in Merlin-deficient grade I meningioma, suggesting that KSR1 also has a role in meningioma tumourigenic signalling." (PMID 32629964, 2020). "The Raf/MEK/ERK pathway contributes to tumour growth in Merlin-deficient tumours, and KSR1 is upregulated in meningioma." (PMID 32629964, 2020). "Here, we aim to further characterise the expression of DCAF1 and KSR1 in Merlin-deficient grade I meningioma (herein referred to as meningioma), and assess the therapeutic potential of targeting these proteins/pathways using the neddylation inhibitor MLN3651, and the MEK1/2 inhibitor selumetinib." (PMID 32629964, 2020). "The researchers found significantly elevated levels of the CRL4-DCAF1 complex and KSR1 protein in meningioma cells compared to normal arachnoid cells." (PMID 39564524, 2024). "In vitro, we observed variability in the DCAF1 and KSR1 expression in cultured primary meningioma cell samples." (PMID 32629964, 2020). "DCAF1 and KSR1 were significantly overexpressed in meningioma cells compared to normal human meningeal cells (HMC) (p < 0.05 and p < 0.01, respectively)." (PMID 32629964, 2020). "We used meningioma tissue and primary cells derived from meningioma tumours to investigate the expression of DDB1 and Cullin 4-associated factor 1 (DCAF1) and KSR1, and confirmed these proteins were overexpressed." (PMID 32629964, 2020). "We then confirmed that KSR1 was significantly increased in meningioma tissue (p < 0.05)." (PMID 32629964, 2020). "There was variation in DCAF1 and KSR1 expression between different meningioma samples." (PMID 32629964, 2020). "Interestingly, DCAF1 knockdown in primary Merlin-deficient schwannoma samples led to a significant decrease in pERK activity, suggesting that Raf/MEK/ERK activity is more dependent on KSR1 activation in schwannoma than in meningioma." (PMID 32629964, 2020). "We investigated both DCAF1 and KSR1 expression in meningioma." (PMID 32629964, 2020). "In addition, the researchers also confirmed that the use of MLN3651 or knocking down DCAF1 can lead to the loss of activity of KSR1 protein in meningioma cells, which in turn lead to the inactivation of the Raf/MEK/ERK pathway, inhibiting the proliferation of meningioma cells." (PMID 39564524, 2024). "We show that DCAF1 knockdown did not change the levels of KSR1 protein in meningioma, and therefore DCAF1 is unlikely to target KSR1 for proteasomal degradation." (PMID 32629964, 2020). "Overall, these results suggest that Raf/MEK/ERK signalling is not dependent on the CRL4-DCAF1-mediated activation of KSR1 in meningioma." (PMID 32629964, 2020). "There could be a feedback mechanism in meningioma that permits pERK1/2 activation independent of KSR1 in DCAF1-depleted cells." (PMID 32629964, 2020). "We confirmed that DCAF1 knockdown in meningioma did not alter KSR1 protein levels." (PMID 32629964, 2020).
pancreas cancer (2 papers, 2017 to 2018). "We found that the loss of KSR1 resulted in a modest, but statistically significant decrease in morbidity; however, all mice eventually succumbed to pancreatic tumors." (PMID 29596465, 2018). "While Ksr1-/- mice were generally older before showing signs of morbidity compared to control animals, all mice eventually succumbed to pancreatic tumors." (PMID 29596465, 2018). "We therefore wanted to determine the effect of KSR1 deletion in a well-characterized mouse model of KRAS-driven pancreatic cancer." (PMID 29596465, 2018). "KSR1 has been shown to impact tumor biology, including in preclinical models of pancreas cancer, as well as response to chemotherapy." (PMID 28732488, 2017). "In this work, we used a genetically engineered mouse model of pancreatic cancer to assess whether KSR1 deletion would influence tumor development in the setting of oncogenic RAS." (PMID 29596465, 2018). "The Kinase Suppressor of Ras-1 (KSR1) is a well-examined scaffolding protein; it has been shown to mediate tumor progression in pancreas cancer and may govern response to treatment." (PMID 28732488, 2017). "We can conclude that in this specific mouse model of pancreatic cancer, KSR1 signaling was not required for tumorigenesis." (PMID 29596465, 2018).
pancreatic ductal adenocarcinoma (2 papers, 2018 to 2025). An infiltrating adenocarcinoma that arises from the epithelial cells of the pancreas. "Supporting this notion, KSR1 expression has been reported to be significantly reduced in pancreatic ductal adenocarcinoma (PDAC) and papillary thyroid carcinoma (PTC) compared with adjacent non-tumorous tissue." (PMID 41155983, 2025). "In this work, we sought to establish whether KSR1 deletion could influence RAS-driven tumorigenesis in vivo using this mouse model of pancreatic ductal adenocarcinoma (PDAC)." (PMID 29596465, 2018).
Allergy (1 paper, 2025). An allergy is an immune response or reaction to substances that are usually not harmful. "Notable genes associated with allergy, immune responses, and inflammation were found (LCK, BACH2, SATB1, LIME1, KSR1, BCL11B, TCF1, and EVL)." (PMID 41394805, 2025).
asthma (1 paper, 2020). "For example, in severe asthma, the combined interaction scores for the STAT3, AGO2, COL1A1, CLCN6, and KSR1 genes yielded a higher interaction for the moderate asthma phenotype, and the JAK2, INSR, ERBB2, NR3C1, and PTK6 genes were more interactive for the severe asthma phenotype." (PMID 32512817, 2020).
Breast tumors (1 paper, 2015). "Breast tumors with a short latency and low levels of pERK1/2 and pMEK showed low levels of total KSR1 and 2, consistent with the reduced phosphorylation of MEK and ERK1/2." (PMID 25853295, 2015).
Crohn disease (1 paper, 2016). A gastrointestinal disorder characterized by chronic inflammation involving all layers of the intestinal wall, noncaseating granulomas affecting the intestinal wall and regional lymph nodes, and transmural fibrosis. "Examples of this sharing of eQTLs between related cell types include a myeloid-specific eQTL for KSR1 (at a GWAS locus for Crohn’s disease) and T cell-specific eQTLs for DEPTOR and HTR6." (PMID 27015630, 2016).
cystic kidney disease (1 paper, 2012). A congenital or acquired kidney disorder characterized by the presence of renal cysts. "Analyses indicated 13 genes, in addition to Nek8 and Ift20 within this area that could potentially result in cystic kidney disease, namely: RGD1309077Phf12, Flot2, Spag5, Sdf2, Supt6h, Proca1, Traf4, Sarm1, Nlk and Ksr1." (PMID 22899815, 2012).
ductal adenocarcinomas (1 paper, 2018). "Overall, the trend toward decreased morbidity with Ksr1-/- mice that we observed was modest and all mice eventually developed invasive ductal adenocarcinoma." (PMID 29596465, 2018). "Histological analysis revealed that these tumors were ductal adenocarcinomas of similar grade to tumors examined from Ksr1+/+ mice, with similar patterns and intensity of pERK and Ki67 staining." (PMID 29596465, 2018).
endometrial carcinoma (1 paper, 2021). A malignant tumor arising from the epithelium that lines the cavity of the uterine body. "KSR1 is highly expressed in human endometrial carcinoma, and the growth of tumor cells is inhibited after knockout of KSR1." (PMID 33461174, 2021).
Glucose intolerance (1 paper, 2011). Glucose intolerance (GI) can be defined as dysglycemia that comprises both prediabetes and diabetes. "This suggests that the mild glucose intolerance of ksr1-/- mice reflects a role for KSR1 in insulin secretion." (PMID 22206009, 2011).
hearing loss (1 paper, 2024). "WT KSR1 mice treated with dabrafenib offered the same amount of protection as both KO KSR1 groups from cisplatin- and noise-induced hearing loss; therefore, dabrafenib is protecting through the MAPK pathway." (PMID 38548338, 2024). "Both dabrafenib treatment and genetic KO of KSR1 prevents this increase and protects mice from hearing loss, which suggests that these cell types are critical in the damage response that leads to hearing loss." (PMID 38548338, 2024). "We hypothesize that these cell types are critical in the stress response that leads to hearing loss because KSR1 KO mice were resistant to cisplatin- and noise-induced hearing loss." (PMID 38548338, 2024). "Previous studies indicate inhibition of the MAPK pathway by dabrafenib confers protection from cisplatin-induced hearing loss, and we sought to determine whether genetic KO of KSR1 and suppression of the pathway provides similar protection." (PMID 38548338, 2024). "Overall, this study shows that knocking out KSR1, as well as inhibiting BRAF, MEK, and ERK, are all promising therapeutic targets to protect from both cisplatin- and noise-induced hearing loss." (PMID 38548338, 2024). "MAPK signaling has been implicated in cisplatin- and noise-induced hearing loss, and here we show that the KSR1 KO mice do not have cochlear structural abnormalities and exhibit normal hearing before damage." (PMID 38548338, 2024). "Thus, either elimination of the KSR1 gene expression or drug inhibition of the MAPK cellular pathway in mice resulted in profound protection from both cisplatin- and noise-induced hearing loss." (PMID 38548338, 2024). "KSR1 is the dominant protein expressed rather than KSR2 which is one of the reasons this genetic mouse model is useful for studying the role of the MAPK pathway in hearing loss." (PMID 38548338, 2024).
hepatocellular carcinoma (1 paper, 2025). A malignant tumor that arises from hepatocytes. "We highlight its structural and functional properties, summarize preclinical evidence for KSR1-targeted interventions, and discuss its therapeutic potential in cancer, with emphasis on hepatocellular carcinoma (HCC)." (PMID 41155983, 2025). "In contrast, studies investigating KSR1 in hepatocellular carcinoma (HCC) have been remarkably limited until recently." (PMID 41155983, 2025). "In contrast, hepatocellular carcinoma (HCC) and clear cell renal cell carcinoma (ccRCC) display marked upregulation of KSR1." (PMID 41155983, 2025).
Listeria monocytogenes infection (1 paper, 2013). "We then tested the impact of KSR1-deficiency on the generation of CD8+ T cell memory in response to Listeria infection, as rapamycin-treatment also enhances CD8 T cell memory in this model." (PMID 23431403, 2013). "However, KSR1-deficient mice displayed normal regulatory CD4+ T cell development, as well as normal memory CD8+ T cell responses to LCMV and Listeria monocytogenes infection." (PMID 23431403, 2013).
liver cancer (1 paper, 2025). An epithelial or non-epithelial malignant neoplasm that arises from the liver. "While most prior studies of KSR1 were performed in non-hepatic cancer models, this work establishes a critical proof-of-concept in liver cancer, underscoring KSR1′s role as a potential oncogenic driver." (PMID 41155983, 2025).
osteosarcoma (1 paper, 2022). A usually aggressive malignant bone-forming mesenchymal neoplasm, predominantly affecting adolescents and young adults. "High KSR1 expression was significantly associated with poor survival in osteosarcoma patients." (PMID 35418575, 2022). "In conclusion, sulfated alginate oligosaccharide exerts antitumor activity and autophagy induction by inactivating MEK1/ERK/mTOR signaling in a KSR1-dependent manner in osteosarcoma." (PMID 35418575, 2022). "Coimmunoprecipitation Co-IP and western blot analysis were performed, and the results revealed that MEK1 coimmunoprecipitated with the KSR1 protein in osteosarcoma cells." (PMID 35418575, 2022). "High KSR1 expression correlated with short overall survival and disease-free survival in osteosarcoma patients." (PMID 35418575, 2022). "In addition, after transfection with HA-tagged KSR1 in osteosarcoma cells, the mRNA and protein expression of KSR1 and MEK1 was significantly upregulated." (PMID 35418575, 2022). "Importantly, univariate analysis showed that KSR1 expression negatively correlated with overall survival and disease-free survival in 100 osteosarcoma patients (P < 0.05)." (PMID 35418575, 2022). "To date, the function of KSR1 in osteosarcoma remains unknown, especially whether KSR1 plays a critical role in AOS-SO4-mediated antitumor activity." (PMID 35418575, 2022). "Furthermore, autophagic flux, TEM, and western blot analysis demonstrated that KSR1 overexpression could restore the antitumor activity of AOS-SO4 in osteosarcoma cells." (PMID 35418575, 2022). "Together, these results suggest that AOS-SO4 has a better antitumor effect in osteosarcoma by inhibiting MEK1/ERK/mTOR signaling, which is KSR1-dependent; thus, AOS-SO4 can be a new potential therapeutic candidate for the treatment of osteosarcoma." (PMID 35418575, 2022). "Therefore, KSR1 could positively regulate the expression of MEK1 in osteosarcoma cells." (PMID 35418575, 2022). "To further determine how AOS-SO4 regulated the MEK1/ERK/mTOR pathway in osteosarcoma, we searched related literature and the STRING website and reported that MEK1 interacted with KSR1, which is also an important autophagy regulator." (PMID 35418575, 2022). "More importantly, we found that KSR1 interacted with MEK1 and functioned as a positive regulator of MEK1 protein in osteosarcoma cells." (PMID 35418575, 2022). "In our research, Co-IP, western blot, and confocal analyses showed that KSR1 specifically interacted with MEK1 and that they were colocalized in osteosarcoma cells." (PMID 35418575, 2022). "To determine the clinicopathological significance of KSR1 in osteosarcoma patients, we performed an IHC analysis of KSR1 in a tissue microarray that included an independent set of 100 pairs of osteosarcoma tissues and adjacent nontumor tissues." (PMID 35418575, 2022). "Furthermore, the confocal analysis revealed that KSR1 and MEK1 were colocalized in osteosarcoma cells." (PMID 35418575, 2022). "To date, the function of KSR1 in osteosarcoma has not yet been reported." (PMID 35418575, 2022). "In addition, the IHC analysis of KSR1 in a tissue microarray that included an independent set of 100 pairs of osteosarcoma tissues and adjacent nontumor tissues indicated that KSR1 was a prognostic marker for osteosarcoma patients." (PMID 35418575, 2022).
pancreatic adenocarcinoma (1 paper, 2023). "However, we found two GEO pancreatic adenocarcinoma datasets (GSE15471 and GSE16515) in which the KSR1 and IQGAP1 transcripts were down-regulated and up-regulated when compared to healthy tissue control, respectively." (PMID 36791195, 2023).
pancreatic carcinoma (1 paper, 2018). "Lastly, antisense oligonucleotides to KSR1 are able to reduce tumor growth of KRAS-dependent human pancreatic carcinoma xenografts in nude mice." (PMID 29596465, 2018). "Another group used antisense oligonucleotides to demonstrate that KSR1 knockdown could reduce growth of KRAS-dependent human pancreatic carcinoma xenografts in nude mice." (PMID 29596465, 2018).
Rectal prolapse (1 paper, 2018). Protrusion of the rectal mucous membrane through the anus. "One unexpected finding that arose during the course of this study was a high frequency of rectal prolapse that occurred in the Ksr1+/+ and Ksr1+/- cohorts (4/22 and 7/17 respectively)." (PMID 29596465, 2018). "4/22 Ksr1+/+ and 7/17 Ksr1+/- mice developed rectal prolapse and were sacrificed for that reason." (PMID 29596465, 2018). "Importantly, exclusion of all animals that developed rectal prolapse from our survival curves did not change the conclusion that Ksr1 deficient animals had a modest increase in survival compared to the Ksr1 wild-type and heterozygous animals." (PMID 29596465, 2018). "We noted that Ksr1+/+ and Ksr1+/- on the PDAC background developed rectal prolapse at a relatively high frequency." (PMID 29596465, 2018). "We do not know why Ksr1-/- mice were protected from the development of rectal prolapse, nor why its incidence has not been documented in other reports." (PMID 29596465, 2018). "Interestingly, none of the Ksr1-/- mice (0/19) on the PDAC background developed rectal prolapse." (PMID 29596465, 2018).
schwannoma (1 paper, 2020). A benign, usually encapsulated slow growing tumor composed of Schwann cells. "KSR1 expression was shown to be increased in Merlin-deficient schwannoma, and is a regulator of proliferation, apoptosis, morphology and adhesion." (PMID 32629964, 2020). "This novel mechanism could explain why DCAF1 knockdown leads to reduced pERK1/2 levels in Merlin-deficient schwannoma, and why combined shRNA knockdown of DCAF1 and KSR1 reduced the proliferation of schwannoma cells." (PMID 32629964, 2020). "Interestingly, KSR1 has a key role in schwannoma pathogenesis; KSR1 knockdown in primary schwannoma led to reduced proliferation, increased apoptosis and altered cell morphology." (PMID 32629964, 2020).